TNF (tumor necrosis factor)
Diseases named in the same sentence as TNF in open-access papers (continued):
Sharing a sentence is not in itself a finding about the gene and the disease.
peritonitis (continued). "Peritonitis due to ΔbgsA led to an excessive induction of TNF-α, IL6, and MIP-2 accompanied by a higher influx of leukocytes in the peritoneum and to increased mortality of infected mice." (PMID 26172831, 2015). "The plasma levels of TNF-α and IL-6 continued rising after 12 h from the induction of peritonitis whereas the reduction of HRV parameters was completed in less than 10 h from the induction of peritonitis." (PMID 26779039, 2015). "Consistent with our in vitro observations, cells isolated from mice with MSU crystal-induced peritonitis showed significantly increased mRNA levels of TNF-α and IL-1β." (PMID 24708712, 2014). "The release of pro-inflammatory mediators can cause acute lung injury and it has been reported that levels of pro-inflammatory cytokines such as IL-6 and TNF-α are significantly elevated in the lungs after CLP-induced peritonitis." (PMID 24830455, 2014). "It confirmed that IL-1, TNFα, IL-6, IL-10 and IFNγ are present at high concentrations in the peritoneal fluid of patients with peritonitis." (PMID 24674057, 2014). "A study done in the rat CLP peritonitis model demostrated a decrease of TNF-α and IL-1β in lungs of animals receiving a prolonged three week pre-treatment with probiotics and overall reduction of acute lung injury was also observed." (PMID 24830455, 2014). "The inhibition of TNF-α production along with a decrease in MPO release due to VPA has also recently been found in a peritonitis paradigm in mice." (PMID 24757498, 2014). "Consistent with other previous reports, our data showed that PDE levels of TNF-α and IL-6 were markedly elevated on the first day of peritonitis." (PMID 23359306, 2013). "We have previously observed such a time course for TNF-α in a rat model of endotoxaemia-induced peritonitis." (PMID 24047433, 2013). "Peritoneal and plasma cytokines (interleukin (IL) 1, tumor necrosis factor α (TNFα), IL-6, IL-10, and interferon γ (IFNγ)) were measured in 66 patients with secondary peritonitis." (PMID 24028733, 2013). "Our results confirm that IL-1, TNFα, IL-6, IL-10 and IFNγ are present at high concentrations in the peritoneal fluid of patients with peritonitis." (PMID 24028733, 2013). "Increased synthesis of hyaluronan in mesothelial cell during peritonitis is attributed to their induction by proinflammatory cytokines and growth factors, in particular, IL-1β IL-6, TNF-α, TGF-β1, and PDGF." (PMID 22577250, 2012). "Apart from hyaluronan, mesothelial cells also synthesize and secrete TGF-β1, IL-1β, IL-6, and TNF-α and their levels are increased during peritonitis." (PMID 22577250, 2012). "Mast cells were shown to produce TNF-α, which recruits neutrophils into the peritoneum in an immune complex peritonitis model." (PMID 22251404, 2012). "Our data showed that the survival and the serum concentrations of IL-6 and TNF-α were all enhanced by NCTD significantly in peritonitis mouse model." (PMID 22984593, 2012). "Elevated levels of TNF-α are found in the peritoneal fluid from CAPD patients undergoing episodes of peritonitis." (PMID 22558080, 2012). "Of note, mice submitted to carrageenan-induced peritonitis exhibited increased IL-1β and TNF-α levels, in contrast to reduced IL-10 levels in peritoneal fluid." (PMID 21799673, 2011). "In the course of peritonitis multiple inflammatory mediators are released locally, including IFNγ and TNFα." (PMID 19675677, 2009). "Interestingly, the highest peritoneal IFNγ and TNFα levels are found in peritonitis caused by highly virulent microorganisms, such as S. aureus, precisely the ones that cause more severe demesothelization and that may lead to irreversible peritoneal injury after a single, severe peritonitis episode." (PMID 19675677, 2009). "In the dialysate of patients with PD-relatedperitonitis and in ascites of liver cirrhosis patients with spontaneousbacterial peritonitis, high levels of various cytokines including TNFα and IL-6 are found due to increasedlocal production." (PMID 18274646, 2007).
peritonitis (continued). "Neutrophil infiltration is a hallmark of peritonitis, and might be induced by the i.p. injection of CXCL1 or TNF α." (PMID 39199274, 2024). "In the peritonitis mouse model characterized by a macrophage phenotype, DW18134 effectively reduced the behavioral score of the peritonitis mice and the secretion of inflammatory factors TNF-α, IL-6, and IL-1β in the serum, with therapeutic efficacy comparable to PF-06650833." (PMID 38675622, 2024). "The levels of TNF-α in a model of acute peritonitis in rats were also investigated." (PMID 36421993, 2022). "We next investigated whether the impaired T cell recruitment observed in the TNF-α–induced peritonitis in STING–/– mice was mediated by STING expressed in mouse heart EC (MHEC) or in T cells, or in both cell types." (PMID 34156982, 2021). "KA inhibits a series of index in LPS-induced peritonitis in mice, such as TNF-α, IL-33, and IL-1β." (PMID 34884814, 2021). "However, it has been demonstrated that, in peritonitis, the biological action of TNF-α was necessary for the host defense and the survival of mice." (PMID 33435569, 2021). "We selected TNF-α as a proinflammatory stimulus, common to diverse inflammatory settings, to induce peritonitis in mice, and we found that T cells were abundantly recruited by 24 hours in WT mice, as previously reported, but were strikingly reduced in global STING–/– mice." (PMID 34156982, 2021). "LBP suppresses the levels of serum TNF-α and IL-6 in LPS-treated mice peritonitis." (PMID 34884814, 2021). "ethanol extract could exhibit an anti-inflammatory effect by inhibiting the production of several proinflammatory mediators, including NO, TNF-α, IL-1β, and IL-6 in LPS-induced peritonitis in vivo and in vitro." (PMID 34931128, 2021). "In addition, γ-terpinene decreased neutrophil migration as well as production of interleukin-1β and TNF-α in carrageenan-induced peritonitis in mice." (PMID 34745922, 2021). "In this model, peritonitis is induced by mixed intestinal flora and a cytokine response, causing ALI29, increased microvascular permeability, and the release of pro-inflammatory mediators including TNF-α, TGF-β1, IL-6, and IL-1β30–32." (PMID 32792558, 2020). "To finally understand whether TPRM7 kinase activity also affects neutrophil transmigration in vivo, we employed a TNF-dependent peritonitis model." (PMID 33658993, 2020). "In peritonitis, treatment with the extract at a dose of 500 mg/kg resulted in a lower total leukocyte count in the peritoneal fluid and blood and lower levels of IL-1β, IL-6, TNF-α and PGE-2 than the control group." (PMID 31830043, 2019). "Notably, IRW exerted beneficial effects against LPS-induced peritonitis, specifically, by reducing the serum levels of tumour necrosis factor (TNF)-α and interleukin (IL)-6 and myeloperoxidase (MPO) activity (P<0.05)." (PMID 30719449, 2019). "The cell experiments showed that KCF18 significantly reduced the binding of proinflammatory cytokines to their cognate receptors, suppressed TNF-α mRNA expression and monocyte binding and transmigration, and alleviated the infiltration of white blood cells in a peritonitis mouse model." (PMID 30783144, 2019). "CX43/P2Y1 dependent modulation of IL-6 secretion may be partially dependent on TNF-alpha since IL-6-promoter is also activated by TNF-alpha among other stimuli explaining the sequence of appearance during peritonitis." (PMID 30735126, 2019). "Furthermore, Ackr1−/− chimeras exhibited reduced tissue infiltration of neutrophils in a TNF-driven peritonitis model and in models of cutaneous inflammation as elicited by local injection of TNF or LPS." (PMID 30446388, 2018). "FTA significantly alleviated peritonitis as evidenced by the decreased number of neutrophils and levels of tumor necrosis factor alpha (TNF-α), interleukin-6 (IL-6), and monocyte chemoattractant protein-1 (MCP-1) in the peritoneal cavity, without interfering with interleukin-10 (IL-10)." (PMID 29509714, 2018).
peritonitis (continued). "In this context, we recently demonstrated that the leaf hydroalcoholic extract obtained from pomegranate is anti-inflammatory as it inhibits TNF-α production and decreases neutrophil migration in a rat model of lipopolysaccharide- (LPS-) induced acute peritonitis." (PMID 29675437, 2018). "In vivo, LA-1 showed a reduction in the infiltration of neutrophils in several rodent models of sterile inflammation including thioglycolate-induced peritonitis, TNF-α-injected cremaster muscle, arterial balloon injury, bile duct injury, and kidney allograft rejection." (PMID 29568527, 2018). "Similar outcomes were observed in a TNF-induced peritonitis model." (PMID 30446388, 2018). "C. latifolia reduced TNF-α and IL-10 levels in zymosan-induced peritonitis." (PMID 27088973, 2016). "In this peritonitis model, mRNAs obtained from whole peritoneal white blood cells showed upregulation of M2 markers Arg1 and MR, and little upregulation of M1 markers iNOS and TNF-α." (PMID 27731330, 2016). "Further investigation of carrageenan-induced peritonitis model revealed that nerolidol decreased the levels of polymorphonuclear cells and tumor necrosis factor (TNF-α) in peritoneal lavage as well as interleukin 1 beta (IL-1b) in LPS-stimulated, peritoneal macrophages." (PMID 27136520, 2016). "Furthermore, STIM2-deficient animals showed decreased macrophage recruitment in the model of Thg-induced peritonitis and reduced TNFα, IL-6, and IL-1β serum levels in LPS-induced inflammation." (PMID 26417434, 2015). "However, antioxidants increased the severity of peritonitis by decreasing the phagocytic efficiency, oxidative burst, and TNF-α production and increasing neutrophil infiltration." (PMID 25253919, 2014). "Accordingly, the association of the usual third-generation cephalosporin with TNF-α blockade during a peritonitis episode may not only slow down the ongoing infection, but also improve survival." (PMID 23527251, 2013). "Importantly, there was a significant positive correlation between PDE levels of HMGB1 and TNF-α, IL-6, as well as WBCs counts during peritonitis." (PMID 23359306, 2013). "Increased levels of TNF-α and Fas ligand during peritoneal inflammation and peritonitis may also induce apoptosis in mesothelial cells." (PMID 22577250, 2012). "At a cellular level, peritoneal mesothelial cells demonstrate impressive adaptability to peritonitis; they effectively clear contaminants into the systemic circulation by promoting margination and migration of neutrophils, and production of proinflammatory cytokines such as IL-6, IL-8 and TNF-α." (PMID 40394329, 2025). "Moreover, we demonstrated that KCF18 decreased the binding of proinflammatory cytokines to their cognate receptors, suppressed TNF-α mRNA expression and monocyte binding and transmigration, and alleviated the infiltration of white blood cells in a peritonitis model." (PMID 30783144, 2019). "Moreover, we would suggest that Nrf2 activation in zymosan-induced peritonitis could limit neutrophil activation and auto-recruitment mainly via the regulation of TNFα, CXCL2 and CCL3 production in the peritoneal fluid." (PMID 31419224, 2019). "In rats whereby TGF-β1 signaling pathways were block by genetic manipulation, E. coli-induced peritonitis exacerbated peritoneal inflammation as demonstrated by increased infiltration of leukocytes and further induction of inflammatory signaling pathways and secretion of TNF-α." (PMID 22577250, 2012). "Taking into account the control group from the postoperative period, we have compared the variation of IL–6 and TNF alpha levels, determined in day 7, with the three categories of diagnostic from that particular period, namely peritonitis with or without septic complications and the control group." (PMID 21776298, 2011). "We also found that CD18 blockade doubled the circulating neutrophil number in TNFα-induced peritonitis, suggesting that CD18 is critical for neutrophil recruitment in peritonitis." (PMID 39199274, 2024).
peritonitis (continued). "In combination with visible peritonitis after the induction of surgery and reproducibly high IL6, IL-10 and TNF-alpha levels in previous studies with the same model, an abdominal infection of the animals is reliably detected." (PMID 39273258, 2024). "The injection of MSU or CPP crystals caused a leucocyte infiltration and an increase in IL-1β, CXCL1, IL-6, TNF-α, and VEGF in lavage fluids from mice with peritonitis, which diminished in the presence of BPI." (PMID 36361854, 2022). "Our results showed that TAK 242 significantly inhibited the production of inflammatory cytokines in the peritoneal lavage fluid of mice with peritonitis, including IL-6, IFN-γ, IL-1β, NO, and TNF-α." (PMID 34884814, 2021). "Using adoptive transfer of SOCS3-silenced macrophages in a mouse peritonitis model, the investigators demonstrated that SOCS3 drives the production of M1-induced cytokines (TNF-α, IL-1β), while reducing the expression of M2-induced IL-10." (PMID 34339354, 2021). "In general, RvDs also block tumor necrosis factor (TNF)-α-induced IL-1β transcripts and are potent regulators of PMN infiltration in brain, skin, and peritonitis in vivo." (PMID 33800694, 2021). "Another study showed that in a mouse peritonitis model, FICZ reduced inflammasome activation and reduced IL6, IL-1β and TNFα levels." (PMID 32439897, 2020). "V. polysphaera extract substantially reduced the levels of proinflammatory mediators such as TNF-α, IL-1β, IL-6 and PGE-2 in λ-carrageenan-induced peritonitis when compared to the stimulated and untreated group." (PMID 31830043, 2019). "On the basis of the finding that knockdown of SLC15A3 decreased TLR4-dependent IL-6 and TNF-α production, SLC15A3 was found to increase in mice with peritonitis, which was positively related to the development of inflammation." (PMID 29991810, 2018). "The peritonitis experimental model was induced by carrageenan following of Myeloperoxidase activity (MPO), Total glutathione and malondialdehyde (MDA), IL-1β and TNF-α levels by spectroscopic UV/VIS analysis." (PMID 29523111, 2018). "In the peritonitis mouse model induced by intraperitoneal injection of MRSA, MCL also suppressed the over-expression of inflammatory cytokines (IL-6, TNF-α, MCP-1 or IFN-γ) and relieved organ damage of liver and kidney." (PMID 28165033, 2017). "In the acute peritonitis mouse model, MCL reduced the secretion of IL-6, TNF-α, IL-1β, MCP-1, IFN-β and IL-10 in sera, and ameliorated lung and liver damage." (PMID 26984741, 2016). "Levels of TNF-α and IL-6 in PDE of controls were almost undetectable, whereas levels of both cytokines markedly elevated in peritonitis patients." (PMID 23359306, 2013). "In parallel analyses, we examined both TNF-α and IL-6 levels in PDE of the first day of peritonitis by ELISA." (PMID 23359306, 2013). "Further, there was a significant positive correlation between HMGB1 levels and WBC counts (r = 0.86, P<0.01), TNF-α level (r = 0.75, P<0.01) as well as IL-6 level (r = 0.81, P<0.01) in PDE of patients with peritonitis." (PMID 23359306, 2013). "Cytokines and chemokines, such as TNF-α and MCP-1, produced by macrophages, are suggested to play important roles for neutrophil influx in thioglycollate-induced peritonitis." (PMID 22251404, 2012). "Additionally, Caulerpa mexicana extracts have shown the ability to reduce pro-inflammatory cytokines such as IL-6, IL-12, TNF-α, and IFN-γ in a zymosan-induced peritonitis mouse model." (PMID 40142455, 2025). "In vivo (LPS-induced peritonitis), MCHLE reduced total leukocyte and neutrophil influx and lowered TNF-α and NO levels to values comparable to dexamethasone; in vitro (LPS-stimulated RAW 264.7), it produced dose-dependent inhibition of TNF-α, IL-1β, and NO." (PMID 41302395, 2025).
peritonitis (continued). "In contrast, there was a remarkable decrease in leukocytes, neutrophils, and the expression of IL-6, IL-1β, and TNF-α in PMB-SA combination groups, indicating the attenuation of the inflammatory response in E. coli-induced peritonitis after PMB-SA combination therapy." (PMID 38258081, 2024). "A study conducted in murine models with peritonitis found that CI FOX significantly reduced pro-inflammatory cytokines, TNF-alpha, interleukin, and neutrophil count in the lungs as well as decreased bacterial burden in the serum when compared to intermittent dosing." (PMID 39728850, 2024). "In rats with carrageenan-induced peritonitis, no significant changes in the levels of TNF-α were observed after a single dose of alginate isolated from C. crinita." (PMID 37103384, 2023). "No significant changes in the levels of TNF-α were observed after a single dose of C. crinita fucoidan in rats with carrageenan-induced peritonitis." (PMID 36421993, 2022). "In vivo analysis using a mouse peritonitis model revealed that mTNs showed anti-inflammatory effects by decreasing levels of pro-inflammatory cytokines in blood (IL-6: 73 ± 4, TNF-α: 42 ± 2%) and peritoneal fluid (IL-6: 78 ± 2, TNF-α: 21 ± 6%)." (PMID 36214916, 2022). "Apart from peritoneal macrophages, MMPs are likely to be produced by neutrophils in septic or even nonseptic peritonitis in consequence of strangulating obstruction and following the upregulation of inflammatory mediators like TNF-α, interleukin-8, and G-CSF." (PMID 33488296, 2021). "In the LPS-induced acute peritonitis mouse model, an increased UDPG level was found, concomitant with the expression of inflammatory cytokines (TNF and IL-6) as well as NO; however, GPI or 6AN treatment resulted in decreased UDPG levels and markedly suppressed expression of inflammatory genes." (PMID 32286295, 2020). "Moreover, acetate also suppressed the secretion of IL-6 and TNF-α in serum and IL-1β in serum and PLF during LPS-induced peritonitis." (PMID 31337751, 2019). "In an in vivo experiment, TRIM31-deficient mice exhibited higher concentrations of IL-1β in the serum, but not of TNF-α or IL-6 in an LPS-induced peritonitis model." (PMID 29868015, 2018). "Monitoring of TNF-α-induced expression of the adhesion molecules VCAM-1, ICAM-1 and E-selectin by flow cytometry was used to confirm NF-κB inhibition in endothelial cells, and thioglycollate-induced peritonitis in mice to confirm effects in vivo." (PMID 24329519, 2014). "Plumericin inhibited NF-κB-mediated transactivation of a luciferase reporter gene (IC50 1 μM), abolished TNF-α-induced expression of the adhesion molecules VCAM-1, ICAM-1 and E-selectin in endothelial cells and suppressed thioglycollate-induced peritonitis in mice." (PMID 24329519, 2014). "Neither E- nor L-selectin appear to mediate leukocyte recruitment in TNF-α induced inflammation or thioglychollate induced peritonitis." (PMID 21835035, 2011). "Regarding the comparison to the control group, the close values for IL–6 can be noticed in the patients with peritonitis but without complications and in the control group or TNF alpha case." (PMID 21776298, 2011). "A significant example in our results is that TAK981 increased kidney dysfunction in lethal endotoxemia but not in mild polymicrobial peritonitis because the increased TNFα (∼300 pg/serum mL) responses in CLP mice were not as strong as that observed in severe lethal endotoxemia (∼5,000 pg/serum mL)." (PMID 37520526, 2023). "In a model of zymosan-induced peritonitis, mice lacking Mcu in the myeloid cells, the Mcu(M)−/− mice, exhibited significantly worse clinical scores, and increased levels of IL-1β and tumor necrosis factor (TNF) in the peritoneal cavity." (PMID 37277641, 2023). "In addition, the concentration of pro-inflammatory cytokines TNF-α, IL-6, IL-1β, KC (CXCL1) and MIP-2 (CXCL2) within the peritoneal lavage also demonstrated that SEMA7A holds protective potential during peritonitis." (PMID 38094294, 2023).